LEP (leptin)
Diseases named in the same sentence as LEP in open-access papers (continued):
Sharing a sentence is not in itself a finding about the gene and the disease.
endometrial cancer (continued). "We also observed a significant linear correlation between circulating ROS values and BMI, leptin, and IL-6 in the type I endometrial cancer patients." (PMID 35053431, 2022). "It should be emphasized that an elevated leptin-to-adiponectin ratio is also an independent factor in the development of endometrial cancer." (PMID 35628118, 2022). "By sub-dividing the patients according to endometrial cancer subtypes, we found that among the type I endometrial cancer patients, BMI, leptin, and IL-6 significantly correlated with T status, N status, and the presence of distant metastases (stage IV)." (PMID 35053431, 2022). "Leptin is involved in endometrial carcinoma cell mitosis, and leptin-mediated effects on endometrial cancer cell cycle progression are concentration-dependent." (PMID 36578551, 2022). "In endometrial cancer, leptin activates STAT3 proteins, which increase their activity in the process of oncogenesis by stimulating proliferation, promoting angiogenesis, and avoiding the control of the immune system." (PMID 35628118, 2022). "Higher P450arom mRNA and protein expression as well as oestradiol concentrations were observed in endometrial carcinoma cells treated with 100 ng/ml leptin, indicating a strong correlation between leptin and P450arom." (PMID 36578551, 2022). "Adiponectin was found to attenuate leptin-elicited SPEC-2 endometrial cancer metastasis by inhibiting the JAK/STAT3 pathway via AMPK activation." (PMID 33799880, 2021). "Our results are consistent with studies reporting high levels of leptin and its receptors in endometrial cancer." (PMID 34202922, 2021). "The conducted analysis showed that leptin expression increased with the grade of endometrial cancer." (PMID 34202922, 2021). "This would help propose strategies based on leptin knockdown or blocking leptin-related pathways in endometrial cancer." (PMID 34202922, 2021). "It is worth noting that we performed an analysis at the transcriptome and proteome levels to show the changes in the expression of leptin and its receptors in endometrial cancer." (PMID 34202922, 2021). "A recent study showed the relationship between markedly elevated leptin levels in patients with higher staging of endometrial cancer (FIGO III and IV)." (PMID 33799622, 2021). "Leptin levels in patients with endometrial cancer were significantly higher than those in the control group." (PMID 33799880, 2021). "This research aimed to assess the impact of cisplatin, depending on the concentration and exposure time, on the expression pattern of leptin in an endometrial cancer cell line." (PMID 32531934, 2020). "An improper level of leptin was also found in the course of endometrial cancer, a common gynecological cancer in women with menopause." (PMID 32531934, 2020). "In endometrial cancer, although LEP and LEPR were more highly expressed in endometrial tumor tissues than normal tissues, there was a suggestion that rates of LEPR positivity were significantly lower among poorly differentiated endometrial tumors." (PMID 32046756, 2020). "The current research aimed to examine changes in the expression leptin and leptin-related genes depending on the concentration of leptin or cisplatin and exposure time of endometrial cancer cells to the drug or leptin." (PMID 32531934, 2020). "The median of FGF21 protein (181.8 pg/mL) as well as leptin (16.9 ng/mL) in patients with endometrial cancer was statistically significant higher compared to median of those proteins among patients from control group (152.1 pg/mL and 14.1 ng/mL, respectively)." (PMID 32570721, 2020). "Having applied multivariate logistic regression analysis for the risk of the development of endometrial cancer, in the final model, independent risk factors were found: BMI, FGF21, and leptin level." (PMID 32570721, 2020).
endometrial cancer (continued). "Next, we examined the variances in the mRNA and protein expression of JAK2 and STAT3 in the Ishikawa endometrial cancer cells treated with 5 μM of cisplatin and 10–40 ng/mL of leptin." (PMID 32531934, 2020). "Ishikawa endometrial cancer cell cultures were incubated with cisplatin, at concentrations of 2.5–10 μM, or leptin in the concentration range 10–40 ng/mL, and for durations of 12, 24 and 48 h compared with the control." (PMID 32531934, 2020). "There are reports saying that the correlation between leptin and endometrial cancer disappears after taking BMI into account." (PMID 32570721, 2020). "Considering the fact that increased body mass, dyslipidemia, and increased leptin levels are factors involved in the pathogenesis of endometrial cancer, one should expect that patients with endometrial cancer should also present with higher levels of FGF23." (PMID 32570721, 2020). "First, such a comprehensive analysis of the effects of cisplatin on the expression of leptin-dependent genes in the endometrial cancer line was performed for the first time." (PMID 32531934, 2020). "As confirmed in numerous studies, the leptin hormone is characterized by positive correlations with the clinical stage of endometrial cancer." (PMID 32570721, 2020). "We also found differences in the median concentrations of both FGF21 and leptin in patients with endometrial cancer compared to those in the median concentration in the group of patients with endometrial polyps." (PMID 32570721, 2020). "In ECC1 and Ishikawa endometrial cancer cells, leptin promotes cell proliferation and invasion through the JAK2-STAT3, PI3K, ERK2, and COX2 pathways." (PMID 33334030, 2020). "It has been found that in endometrial cancer cells, leptin suppressed the expression of LSR, while adiponectin increased its expression." (PMID 31330820, 2019). "C-peptide, insulin, C-reactive protein, leptin, IL-1Ralpha, and IL-6 decreased significantly, while SHBG, IGFBP1, and adiponectin increased significantly in weight-loss interventions in endometrial cancer." (PMID 31440472, 2019). "Leptin also promotes the proliferation and invasion of endometrial cancer cells by activating STAT3 and ERK1/2, JNK signaling pathways." (PMID 31440472, 2019). "Leptin is involved in facilitating endometrial cancer progression and metastasis of pancreatic cancer via the activation of JAK2/STAT3 pathway." (PMID 31330820, 2019). "The upregulation of LSR expression by these drugs contributed to the suppression of motility and invasion of endometrial cancer cells enhanced by leptin administration." (PMID 31330820, 2019). "Adiponectin, also known as Acrp30, inhibited the leptin-promoted SPEC-2 endometrial cancer metastasis by inactivating JAK/STAT3 pathway via AMPK activation." (PMID 29682217, 2018). "In an in vitro study, leptin treatment resulted in increased proliferation of hormone-responsive Ishikawa/ECC1 type-I endometrial cancer cells." (PMID 30510663, 2018). "Several clinical studies have suggested that leptin and Ob-R play a role in the pathological processes of endometrial cancer." (PMID 30510663, 2018). "In different endometrial cancer cell lines, laboratory findings also have demonstrated leptin’s link to various neoplastic phenomena such as cellular proliferation, angiogenesis, and oestrogenic activity." (PMID 30510663, 2018). "A study, which investigated the role of leptin in the process of programmed cell death in endometrial carcinoma, observed that leptin induced a decrease in apoptosis in Ishikawa and HEC-1A cells." (PMID 30510663, 2018). "LSR expression in normal and endometrial cancer cells was regulated by the adipokines leptin and adiponectin." (PMID 27036040, 2016). "Serum concentrations of leptin are reportedly higher, and those of adiponectin lower, in patients with endometrial cancer compared with the control subjects." (PMID 24944677, 2014).
endometrial cancer (continued). "Secondly, the present study was unable to assume that correlations exist between serum adiponectin or leptin levels and the expression of AdipoRs and ObR in patients with endometrial carcinoma." (PMID 24944677, 2014). "Direct relationships between leptin and IL-1 system have been detected in vitro in breast and endometrial cancer cells." (PMID 24202338, 2013). "It is noteworthy that significantly higher levels of leptin have been found in obese endometrial cancer patients compared to those with a normal endometrium." (PMID 22731395, 2012). "Leptin peptide receptor antagonist 2 treatment decreased the levels of leptin-induced angiogenic molecules in mouse tumors and human endometrial cancer cells." (PMID 19531256, 2009). "The effect of leptin on endometrial cancer carcinogenesis is due to leptin-induced cell growth of endometrial cancer." (PMID 21566743, 2008). "It should be noted that the assessment of leptin levels as a risk factor for endometrial cancer is not typically performed in routine clinical practice." (PMID 41375041, 2025). "Using qRT‐PCR analysis, endometrial cancer tissues (n = 39) exhibited higher expression levels of adiponectin, leptin, IL6, TNFα, and their receptors, IL6R and TNFRSF1A/B, compared to the calibrator sample, which consisted of five pooled benign endometrial control samples." (PMID 40642843, 2025). "It is noteworthy that we find that leptin is associated with increased risk of endometrial cancer in diabetic patients only (ORQ4 vs. Q1 = 3.787, 95% CI 0.903–15.876, p = 0.069), suggesting a role for leptin in elevating the risk of endometrial cancer in diabetic individuals." (PMID 38339282, 2024). "Leptin is one of the markers used to diagnose endometrial cancer." (PMID 37600567, 2023). "Interestingly, some investigators found in endometrial cancer tissue higher circulating levels of leptin and its receptor (Ob/ObR) in comparison with normal endometrial tissue." (PMID 37509120, 2023). "For endometrial cancer, there was positive mediating effect through estradiol, while with less certainty, the estimates were also indicative of possible mediating effects through insulin, and leptin and CRP." (PMID 35048536, 2022). "Interestingly, the PI3K/AKT/mTOR pathway mediates signaling from leptin and IL-6, which, in our study, have been found to be significantly elevated in type I endometrial cancer patients and positively correlated with tumor prognostic factors." (PMID 35053431, 2022). "Plasma leptin and IL-8 levels in patients with endometrial cancer and control patients." (PMID 36505829, 2022). "Leptin and its receptor (ObR) have been found in several cancers, including endometrial cancer." (PMID 35053431, 2022). "Leptin demonstrates a stimulatory effect on endometrial cancer cell invasion." (PMID 34951691, 2022). "Further studies of leptin and adiponectin signalling pathways and their “cross talk” with oestradiol may allow for the development of an effective targeted therapy in endometrial cancer." (PMID 35628118, 2022). "Only one study to date has examined the relationship between adipokines (leptin and adiponectin) and endometrial cancer survival and did not observe an association between adiponectin levels and overall survival in women with type 1 endometrial cancer." (PMID 35174651, 2022). "Leptin has been demonstrated to promote endometrial cancer cell proliferation in various studies." (PMID 34951691, 2022). "A positive correlation was noted between endometrial cancer and elevated serum leptin levels." (PMID 36578551, 2022). "The levels of various adipokines, such as leptin, visfatin, galectin, resistin, adiponectin, and vaspin, are increased or decreased in endometrial cancer and significantly correlated with cancer progression." (PMID 36578551, 2022). "Elevated levels of leptin and its receptors may potentially contribute to the progression of endometrial cancer." (PMID 34202922, 2021).
endometrial cancer (continued). "Higher serum leptin levels in patients with endometrial cancer are well documented, and may be considered as an independent risk factor for endometrial cancer." (PMID 33799622, 2021). "Moreover, vaspin was found to have the greatest specificity and sensitivity for endometrial cancer (83% and 89%, respectively) when compared to other adipokines, including leptin, galectin-3 and omentin-1." (PMID 33799622, 2021). "Similarly, with whole blood, an increase in the level of leptin and its receptors was also observed in patients with endometrial cancer." (PMID 34202922, 2021). "Determining leptin levels may appear to be one of the useful molecular markers for selecting a dose of cisplatin in endometrial cancer treatment and predicting treatment success." (PMID 32531934, 2020). "Analysis of changes in the level of leptin in endometrial cancer cells exposed to cisplatin at the protein level showed that the statistically significant differences were visible for cells treated with 2.5 μM of cisplatin after only 48 h in comparison to the control (p = 0.0031)." (PMID 32531934, 2020). "Many studies have shown higher levels of leptin in patients with endometrial cancer." (PMID 32570721, 2020). "Therefore, leptin should be determined in vivo in patients with endometrial cancer before, during and after cisplatin treatment in the subsequent stages of the study." (PMID 32531934, 2020). "Therefore, future analysis ought to be focused on analyzing changes in the morphology of the Ishikawa endometrial cancer cell line under cisplatin and leptin treatment by using more precise methods, such as the DAPI assay." (PMID 32531934, 2020). "Also, the overexpression of leptin and leptin receptors was related to the development and the degree of gastric cancer, and endometrial cancer." (PMID 32573960, 2020). "In addition, our current study has confirmed earlier reports that higher levels of leptin are found in patients with higher the degree of advancement of endometrial cancer and lower levels of histopathological differentiation." (PMID 32570721, 2020). "Three more recent meta-analyses have reported that adiponectin levels and leptin/adiponectin ratio are considered as predictive and prognostic biomarkers in order to guarantee early diagnosis and disease monitoring of endometrial cancer, especially in postmenopausal women." (PMID 31052147, 2019). "Elevated leptin levels suggest the presence of endometrial cancer, and serum leptin levels may be an effective tool for assessing the clinical staging of endometrial cancer." (PMID 31440472, 2019). "Studies have shown that the expression of ObR in poorly differentiated endometrial cancer tissues is significantly higher than that in well-differentiated endometrial cancer tissues, and leptin can inhibit the apoptosis of endometrial cancer cells by activating the NIK/IKK signaling pathway." (PMID 31440472, 2019). "Other studies have reported that the leptin-2548 G/A SNP may be involved in the occurrence and development of endometrial cancer." (PMID 31440472, 2019). "In a study where immunohistochemical expressions of leptin, Ob-R and hypoxia-inducible factor-1α (HIF-1α) were analyzed in endometrial cancer tissue, immunoreactivity for leptin and Ob-R protein was observed in 56.7% and 30.0% of endometrial cancer cases, respectively." (PMID 30510663, 2018). "Moreover, the investigators found that leptin potently induced invasion of endometrial cancer cells in a matrigel invasion assay." (PMID 30510663, 2018). "Furthermore, in the present study, downregulation of LSR by the siRNA and the leptin-treatment in endometrial cancer cells induced cell migration and invasion." (PMID 27036040, 2016). "Leptin also positively regulated endometrial cancer growth via JAK/STAT and AKT pathways." (PMID 27185268, 2016). "Leptin has also been suggested to have a role in uterine and endometrial cancers." (PMID 21338489, 2011).
endometrial cancer (continued). "In endometrial cancer cells leptin induces the expression of IL-1 system." (PMID 21139583, 2011). "Leptin enhances the expression of cell cycle regulators cdk-2 and cyclin D1 in human BC cells and of pro-angiogenic factors in mouse mammary and endometrial cancer cells." (PMID 19531256, 2009). "This can increase circulating estrogen and leptin levels, which have been shown to promote tumor development by enhancing cell proliferation, supporting angiogenesis, and inhibiting apoptosis, particularly in hormonally driven cancers such as breast and endometrial cancer." (PMID 41514674, 2026). "Therefore, strategies aimed at improving the A/L ratio by concurrently elevating adiponectin and reducing leptin levels may be a more effective approach for the management of endometrial cancer." (PMID 38339282, 2024). "Thus, oestradiol, directly on the endometrium and indirectly increasing the effect of leptin, may contribute to the development of endometrial cancer." (PMID 35628118, 2022). "Exposure to leptin could alter endometrial cancer cell morphology." (PMID 36578551, 2022). "In the present study, we aimed to investigate the correlation between BMI, leptin, the proinflammatory cytokines IL-6 and TNFα, reactive oxygen species (ROS), and the traditional prognostic factors T, G, N and M status among type I endometrioid and type II endometrial cancer patients." (PMID 35053431, 2022). "Thus, leptin becomes the cytokine responsible for the proliferation of endometrial cancer." (PMID 35628118, 2022). "The role of leptin as a potential cell growth factor was reported in a study from 2013 where it was proven that leptin, by increasing the expression of aromatase P450 and the local formation of estrogen, makes a significant contribution to enhancing the proliferation of endometrial cancer cells." (PMID 33799622, 2021). "However, whether the leptin signaling pathway can influence the development of endometrial cancer by affecting the classical estrogen signaling pathway remains to be further confirmed." (PMID 31440472, 2019). "Additionally, leptin and Notch signaling seem to crosstalk in endometrial cancer." (PMID 30004402, 2018). "Indeed, leptin has been shown to have an important role in cell proliferation, invasion, metastasis and/or survival in several cancer types, such as breast, liver, colon, esophageal and endometrial cancers, including a role in ovarian cancer proliferation." (PMID 29212170, 2017). "Leptin could exert autocrine effect to stimulate endometrial cancer progression." (PMID 21566743, 2008). "In 12 lymph nodes (4 cancerous and 8 non‐cancerous), significantly higher adiponectin (p = 0.0002), leptin (p = 0.011), and IL6R (p = 0.009) expression was observed compared to endometrial cancer tissue." (PMID 40642843, 2025). "In comparison to normal endometrium used as a reference or calibrator, the expressions of all the adipocytokines—adiponectin, leptin, IL6, and TNFα—were found to be much higher in endometrial cancer tissue." (PMID 40642843, 2025). "Both leptin and HIF-1 activate STAT (signal transducer and activator of transcription) proteins, which are related to the invasiveness of the endometrial cancer cell line." (PMID 35628118, 2022). "After being treated with inhibitors (AG490, U0126, LY294002, and NS398) respectively, stimulated endometrial cancer cell proliferation and increased COX-2 protein expression induced by leptin were abolished." (PMID 36578551, 2022). "A positive correlation between overexpression of leptin and hypoxia-inducible factor 1 alpha (HIF-1α), an indicator of tissue hypoxia consisting of two subunits, was clearly observed in endometrial cancer tissues." (PMID 36578551, 2022). "In our studies, we were able not only to observe higher serum levels of leptin and FGF21 in endometrial cancer patients but also to confirm the correlation of FGF21 levels with cancer stage and grade in these patients." (PMID 32570721, 2020).